C3 (complement C3)
Diseases named in the same sentence as C3 in open-access papers (continued):
Sharing a sentence is not in itself a finding about the gene and the disease.
colorectal cancer (9 papers, 2008 to 2023). A primary or metastatic malignant neoplasm that affects the colon or rectum. "Further subgroup analysis showed that the levels of C3 expression had significantly positive effect on colorectal cancer recurrence in patients during early TNM stages (p = 0.002) and those without spread to lymph nodes (p = 0.009)." (PMID 34722636, 2021). "This revealed that clinical CRC samples with higher C3 expression were enriched for the general pathway of colorectal cancer development and progression." (PMID 34722636, 2021). "Serum levels of biomarkers specifically reflecting type I (C1M), type III (C3M) and type IV (C4M) collagen degradation and type III collagen formation (Pro-C3) were measured in healthy controls, subjects with adenomas and colorectal cancer patients." (PMID 27465284, 2016). "In detail, the level of C1M and Pro-C3 were significantly elevated in colorectal cancer patients compared to healthy controls (C1M: p < 0.001, Pro-C3: p < 0.0001) and subjects with adenomas (C1M: p <0.0001, Pro-C3: p <0.0001)." (PMID 27465284, 2016). "To explore the impact of C3 gene expression on the tumor immune microenvironment, we employed the CIBERSORT algorithm to compare the abundance of 22 human infiltrating immune cell types between colorectal cancers with C3 gene expression above and below median level." (PMID 34722636, 2021). "Therefore, we propose that C3 represents a candidate biomarker for poor prognosis in colorectal cancer patients." (PMID 34722636, 2021). "Specific fragments of degraded type I, III and IV collagen (C1M, C3M, C4M) and type III collagen formation (Pro-C3) were assessed in serum from colorectal cancer patients, subjects with adenomas and matched healthy controls using well-characterized and validated ELISAs." (PMID 27465284, 2016). "To explore the impact of C3 gene expression on resistance to FOLFOX chemotherapy, we assessed the correlation between C3 gene expression in different colorectal cancer cell lines and the corresponding IC50 of 5-Fluorouracil and Oxaliplatin." (PMID 34722636, 2021). "In a study of individuals with and without colorectal cancer it was found that the blood concentration of the complement C3a-desArg is elevated in individuals with either colorectal polyps or colorectal cancer." (PMID 19091087, 2008).
cystic fibrosis (9 papers, 2015 to 2026). Autosomal recessive disorder caused by pathogenic variants in the CFTR gene (cystic fibrosis transmembrane conductance regulator), which encodes a chloride and bicarbonate channel expressed in epithelial cells, and follow the diagnosis criteria. "The same study found increased intracellular C3 in airway epithelial cells in end-stage lung disease due to cystic fibrosis or chronic obstructive pulmonary disease." (PMID 35784369, 2022). "Production but also storage of C3 by AEC might have important implications also for end‐stage lung diseases such as cystic fibrosis and chronic obstructive pulmonary disease in which C3 stores in AEC are found to be increased." (PMID 32246830, 2020).
diabetic retinopathy (9 papers, 2012 to 2026). "Patients with glomerular C3 deposition had a higher prevalence of diabetic retinopathy, lower serum albumin level, lower serum C3 level, and more severe pathologic phenotype of DN than those without such deposition." (PMID 35711407, 2022). "However, the expression of complement regulatory proteins causes the increased deposition of C3 (complement component 3) and activation of the membrane attack complex thereby leading to diseased conditions like corneal inflammation, AMD or diabetic retinopathy." (PMID 28450823, 2017). "Further, intense staining of complement proteins in the retinal tissues of diabetic donors with early vascular/DR changes as compared to control non-diabetic donor retina confirmed the role of CFH and C3 in diabetic retinopathy." (PMID 32117292, 2020).
endothelial dysfunction (9 papers, 2019 to 2025). In vascular diseases, endothelial dysfunction is a systemic pathological state of the endothelium (the inner lining of blood vessels) and can be broadly defined as an imbalance between vasodilating and vasoconstricting substances produced by (or acting on) the endothelium. "This C3 mutation results in systemic complement activation and endothelial dysfunction, culminating in a renal TMA." (PMID 30714990, 2019). "C3a and C5a are potent anaphylatoxins that induce endothelial dysfunction and neutrophil activation, known as an effector function of complement, while C3b is a key subunit in the C3 convertase required for complement propagation." (PMID 39696469, 2024). "Endothelial dysfunction might reflect alterations in the HDL proteome, including enrichment in inflammatory proteins, such as SAA, complement C3, apoC-III and/or a depletion of apoJ and apoA-IV." (PMID 30842338, 2019).
glioblastoma (9 papers, 2006 to 2026). The most malignant astrocytic tumor (WHO grade IV). "Exposing human glioblastoma cells to Transforming Growth Factor-β (TGF-β) for 24 h resulted in increased mRNA levels of C3, C3aR, CTSL, and other growth factors." (PMID 38894892, 2024). "CTSL, which cleaves intracellular C3 into biologically active C3a and C3b, has been reported to contribute to glioblastoma malignancy, which supports the role of proteases in mediating glioblastoma invasiveness." (PMID 38894892, 2024). "Single-cell RNA sequencing from five primary glioblastoma cells showed intra-tumoral heterogeneity and expressed complement pathway genes, including C3." (PMID 38894892, 2024). "Further support for the idea that C3 transcription in the CNS is indeed driven by C/EBPD was obtained by ectopic expression of C/EBPD in the human glioblastoma cell line U-373 MG, which expresses the astrocyte marker GFAP." (PMID 26230261, 2015). "Vice versa, transfection of the human glioblastoma cell line U-373 MG with a C/EBPD expression vector led to a significant upregulation of C3, CXCL9, CP, CCL3, TNFAIP6, and IL-6 mRNA levels." (PMID 26230261, 2015). "Similarly, FH-like protein 1 (FHL-1), a truncated form of Factor H that retains inhibitory activity against C3, is secreted by glioblastoma cells in vitro." (PMID 34671342, 2021). "A combination therapy for glioblastoma should also target the NLRP3 inflammasome pathway, which induces tumor metastasis in response to S1P/S1PR1 and C3 complement signaling." (PMID 38894892, 2024). "We and others have previously shown in vitro that several glioblastoma cell lines (T98G, CB193, U105MG) produce abundant levels of C3 (as well as factor B and factor D), particularly in response to T/NK cell-derived IFN-γ." (PMID 37174113, 2023). "Moreover, C3, which is the common point of the three initiating pathways of the complement system, was abundantly present in necrotic and non-necrotic areas of glioblastomas." (PMID 40867623, 2025).
heart failure (9 papers, 2013 to 2025). Inability of the heart to pump blood at an adequate rate to meet tissue metabolic requirements. "Cox regression models adjusted for covariates in a cohort of 185 heart failure patients identified complement and coagulation-related proteins (C3, C7, C8, C9, F9) as significant predictors of disease progression." (PMID 41158877, 2025). "Consistently, cardiac failure and fibrotic markers were significantly upregulated in the cardiac-specific C3 knockout mice compared with the liver-specific C3 knockout mice." (PMID 36109509, 2022). "We also included 3 patients (2 females of 20 and 28 years and 1 male of 38) with heart failure due to prior myocarditis as positive controls for confirmation of the presence of IgG and C3 in heart disease with established immunological etiology." (PMID 32850816, 2020). "Mature IgG2a auto-antibodies specific for cardiac antigens are present in rat heart failure serum, and IgG and complement C3 deposits are evident in heart failure tissue of both rats and human patients." (PMID 32850816, 2020). "An increased amount of deposited C3 cleavage products C3b/iC3b/C3c induces the second inflammatory phase after trauma, resulting in cardiac failure and death." (PMID 32117238, 2020). "Complement C3 is a central effector pathway of the innate immune system that plays an important role in cardiac remodelling and heart failure." (PMID 31844116, 2019). "Additionally, after PAC, C3−/− mice showed a reduction in the fibrotic area, cardiac failure, and fibrotic marker gene expression in the right ventricle compared with WT mice." (PMID 36109509, 2022). "Further clinical correlation studies will be needed to establish whether circulating C3 levels might become a useful tool to help predicting susceptibility to aggressive myocarditis, and possibly its progression to DCM and heart failure." (PMID 23460527, 2013). "The increases in C3 in human patients with CHF is related to chronic immune-inflammatory activation, leading to adverse left ventricular remodeling and aggravation of heart failure, and poorer outcome." (PMID 35203200, 2022).
Hepatic steatosis (9 papers, 2008 to 2025). Steatosis is a term used to denote lipid accumulation within hepatocytes. "C3 deficiency has been shown to impart protective effects against ethanol-induced hepatic steatosis and inflammation." (PMID 31076642, 2019). "Post-therapy BMI, alanine aminotransferase, TC, C4 levels, white blood cell counts, and hepatic steatosis were independently associated with the post-therapy C3 levels of SVR patients." (PMID 27870883, 2016). "Ethanol exposure enhances C3 hydrolysis, and complement receptor 2 (CR2)-Crry-mediated inhibition of C3 activation ameliorates hepatic steatosis." (PMID 40474973, 2025). "MASLD patients exhibit high levels of complement C3, which is positively correlated with the severity of fatty liver." (PMID 40422243, 2025). "CR2-Crry inhibits C3 convertase and thus suppresses C3 cleavage and activation, leading to a reduction in both inflammatory cytokine levels and hepatic steatosis after ethanol feeding." (PMID 31076642, 2019). "Taken together, the data elucidate the molecular mechanisms whereby C3 regulates liver steatosis and inflammation." (PMID 31076642, 2019). "Moreover, C3 deletion inhibits hepatic steatosis induced by alcohol in mice." (PMID 27550859, 2016). "Together, these findings suggest a protective role for C3/C3 peptides and C5L2 against the development of hepatic steatosis." (PMID 24796007, 2014). "Thus, in our study, we set out to and succeeded in demonstrating a direct correction between C3 levels (rather than the activated complement components) and Fatty Liver Disease in a large sample of Chinese adults." (PMID 25856141, 2015).
hyperlipidemia (9 papers, 2010 to 2024). "The few studies that have examined complement C3 gene expression in adipose tissue have demonstrated associations with BMI, adipose tissue site, insulin sensitivity, age and postprandial lipemia." (PMID 20105310, 2010). "In addition, hyperlipidemia was positively correlated with elevated levels of C3, C4, C1q, and FH proteins." (PMID 35370615, 2022).
injury (9 papers, 2008 to 2025). Damage inflicted on the body as the direct or indirect result of an external force, with or without disruption of structural continuity. "Chest trauma led to elevated expression levels of inflammatory and coagulatory proteins (such as TNFα receptor, IL-1α, IL-1β, C3, NF-κB and plasminogen activator)." (PMID 26303896, 2015). "We hypothesized that C3 increase after IRI can promote neutrophils to release NETs, which further plays an important role during ischemia-reperfusion induced renal injury, and that C3 KO may inhibit NETs release and protect renal function." (PMID 35250972, 2022). "Consistent with the hypothesis that the C3 gene could play an important role as mediator of the proinflammatory effect of C/EBPβ, some data in the literature implicate C3 as an active factor in neuronal damage in experimental models of inflammation and traumatic brain injury." (PMID 27769255, 2016). "In accordance with this hypothesis, immune complex-induced skin injury and peritonitis were found to be dependent on MC and C5aR, but not C3aR or C3." (PMID 18559098, 2008).
multiple myeloma (9 papers, 2018 to 2025). "C3 IGHG4+ Myeloma cells mainly playing the role of Influencer, Monocytes Macrophages Play the roles of Receiver and Influencer." (PMID 40406148, 2025). "This analysis resulted in the identification of four distinct cell subsets: C0 IGLL5+ Myeloma Cells, C1 IGHG4+ Myeloma Cells, C2 MALAT1+ Myeloma Cells, and C3 IGHG1+ Myeloma Cells." (PMID 39281682, 2024). "Thus, patients with renal injury in multiple myeloma with low complement C3 levels should undergo renal biopsy to determine the type of renal pathology." (PMID 33482806, 2021). "We next looked at the APP signaling network, and the findings indicated that monocyte/macrophages, C3 IGHG4+ myeloma cells, and C0 IGLC3+ myeloma cells had substantial relationships with one another." (PMID 40406148, 2025). "The four identified cell subgroups were as follows: C0 IGLL5+ Myeloma Cells (724 cells), C1 IGHG4+ Myeloma Cells (310 cells), C2 MALAT1+ Myeloma Cells (305 cells), and C3 IGHG1+ Myeloma Cells (149 cells)." (PMID 39281682, 2024). "All patients with unknown etiology were screened for autoimmune systemic disorders and multiple myeloma with serological tests, such as ANA, Anti-ds DNA, ANCA, serum C3, C4, and protein electrophoresis." (PMID 39190047, 2025).
neuromyelitis optica spectrum disorder (9 papers, 2021 to 2026). "Several inhibitors targeting C1, C3, C5, and C5a have undergone development and received approval for clinical applications, although only anti-C5 therapies have received approval for CNS indications (generalized myasthenia gravis and neuromyelitis optica spectrum disorder)." (PMID 41261092, 2025).
neutropenia (9 papers, 2012 to 2024). A decrease in the number of neutrophils found in the blood. "Patients with higher serum levels of IL-17F showed neutropenia, granulocytopenia, elevated IgG, and decreased C3." (PMID 28210632, 2017). "Furthermore, associations between a positive IFN score and rheumatoid factor (RF), low complement C3 or C4 and neutropenia has been described." (PMID 34335613, 2021). "Laboratory investigations revealed neutropenia, an elevated erythrocyte sedimentation rate (ESR), presence of lupus anticoagulant, low complement component 3 (C3), and presence of perinuclear anti-neutrophil cytoplasmic antibody (p-ANCA)." (PMID 23186390, 2012).
pemphigoid (9 papers, 2018 to 2025). "Definitive differentiation was achieved through histopathology and direct immunofluorescence, which demonstrated intraepithelial acantholysis with IgG and C3 deposition, thereby excluding pemphigoid and supporting a diagnosis of PNP." (PMID 41531591, 2025). "In a case report of pemphigoid with interstitial lung disease, linear deposits of IgG and C3 were found in the alveolar basement membrane by direct immunofluorescence on a lung biopsy." (PMID 39037699, 2024). "Certain authors support that C3-positive pemphigoids in DIF are mediated by IgG1/IgG3 and IgG4, and they would present as the classic BP with urticarial rash and worse clinical severity." (PMID 38069109, 2023). "Diseases of the pemphigoid sub-family show a linear deposition pattern of IgG and/or C3 at the BMZ of epithelial tissue by DIF, due to the hemidesmosomal location of antigens targeted in these diseases." (PMID 38074463, 2023). "Depending on the location of the Ig or C3 deposits, pemphigus (deposits in the intercellular space, also termed honeycomb pattern), or pemphigoid (linear staining along the dermal-epidermal junction) are differentiated." (PMID 33505392, 2020). "If clinically suspected, the detection of tissue-bound autoantibodies (or C3) in a perilesional skin (or mucosal) biopsy is the gold standard for the diagnosis of pemphigus and pemphigoid." (PMID 33505392, 2020). "Accordingly, in previous reports of IgM pemphigoid with bullous phenotype, linear deposits of complement C3 at the BMZ were consistently detected alongside IgM autoantibodies, whereas the presence of skin‐bound C3c did not necessarily result in clinical blisters." (PMID 40765425, 2025). "Therefore, it seems tempting to infer that IgM pemphigoid might be exacerbated or undergo phenotypical shifts by further contribution of complement C3 and possibly IgG and/or IgA autoantibodies." (PMID 40765425, 2025). "Similar DIF findings of linear deposition of IgG and C3, n-serration, and mixed reliability of IIF in anti-p200 pemphigoid often result in misdiagnosis." (PMID 34684098, 2021). "On the other hand, C3-negative pemphigoids are IgG4-dominant and tend to have a non-inflammatory phenotype with milder severity." (PMID 38069109, 2023). "It needs to be established in further studies whether the diagnosis of IgM pemphigoid requires the lack of additional IgG, IgA, and C3 reactivity by direct IF microscopy like in the present study or, in line with LAD, also includes patients with weak IgG, IgA, and/or C3 deposits." (PMID 40765425, 2025).
pulmonary arterial hypertension (9 papers, 2011 to 2025). Pulmonary arterial hypertension (PAH) is a group of diseases characterized by mean pulmonary artery pressure >20 mmHg and elevated pulmonary arterial resistance leading to right heart failure. "A recent study identified the alternative complement pathway as a key mediator of PAH using both samples from PAH patients as well a mouse model of pulmonary hypertension in mice deficient for various complement factors, C3, C5 and factor H." (PMID 38178176, 2024). "Meanwhile, another study showed that right ventricular systolic pressure and right ventricular hypertrophy are attenuated in C3–/– hypoxic mice, suggesting that C3 deficiency attenuates chronic hypoxia-induced pulmonary arterial hypertension in mice." (PMID 36653797, 2023). "In addition, complement components C3 and C4a have been implicated as biomarkers of idiopathic pulmonary hypertension." (PMID 22194859, 2011). "Her positive rheumatoid factor, low C3 and low C4 complement levels, and elevated creatinine kinase suggest that she may have had mixed connective tissue disease that presented as isolated pulmonary hypertension." (PMID 38975377, 2024). "In 2020, a study showed that a high FDG uptake in pulmonary arterial hypertension (PAH) in patients with SLE correlated with SLE disease activity and the immune/inflammatory status (C3 and C4 levels)." (PMID 36431192, 2022). "Our data suggest that complement activation may play a role in stimulating IL-6 production in pulmonary hypertension since IL-6 expression was increased in hypoxic WT mice but not in C3 −/− mice." (PMID 22194859, 2011).